GAB3 (GRB2 associated binding protein 3)
Tractability: PROTAC: ubiquitination databases record sites on it.
Gene: Protein-coding gene on chromosome X (154,675,249 to 154,751,583, reverse strand). Ensembl gene ENSG00000160219.
Subcellular location (Human Protein Atlas): Nuclear speckles; Cytosol; Nucleoplasm
Pathways (Reactome):
Immune System: Signaling by CSF1 (M-CSF) in myeloid cells
Gene Ontology:
Molecular function: protein binding; signaling adaptor activity
Biological process: signal transduction
Cellular component: cytoplasm
Homologues: Orthologues: chimpanzee GAB3 (99% identical), macaque GAB3 (98% identical), rabbit GAB3 (85% identical), guinea pig GAB3 (78% identical), mouse Gab3 (78% identical), pig GAB3 (76% identical), tropical clawed frog gab3 (58% identical), Drosophila melanogaster dos (24% identical), Caenorhabditis elegans soc-1 (15% identical), zebrafish si:ch73-149c21.1 (13% identical). Paralogues in human: GAB2 (37% identical), GAB1 (33% identical), GAB4 (25% identical), PHLDB1 (20% identical), PHLDB2 (15% identical), PLEKHS1 (12% identical), PHLDB3 (6% identical).
Diseases named in the same sentence as GAB3 in open-access papers:
GAB3 is named in the same sentence as 11 diseases in open-access papers, as found by Europe PMC text mining. Sharing a sentence is not in itself a finding about the gene and the disease. The quoted sentences say what the papers report.
colitis (3 papers, 2019 to 2021). Inflammation of the colon. "However, it was recently suggested that GAB2 and GAB3 may perform redundant functions in immune cells, given that Gab2/3−/− mice exhibit T cell- and macrophage-mediated colitis whereas Gab2−/− and Gab3−/− mice do not." (PMID 33763075, 2021).
glioma (2 papers, 2017 to 2022). A benign or malignant brain and spinal cord tumor that arises from glial cells (astrocytes, oligodendrocytes, ependymal cells). "GAB3 was also reported to promote tumor progression, particularly in ovarian cancer, colorectal cancer, and glioma." (PMID 36275756, 2022). "Second, glioma cell growth was inhibited by Gab3 knockdown, but was augmented with Gab3 overexpression." (PMID 28291820, 2017). "The quantified blot results of all seven sets of tissues were integrated.Gab3 expression in cultured human glioma cells was also tested." (PMID 28291820, 2017). "In both established (U251MG cell line) and primary human glioma cells, Gab3 knockdown by shRNA/siRNA significantly inhibited Akt activation and cell proliferation." (PMID 28291820, 2017). "Third, in human glioma cells, Gab3 is required for the activation of Akt, which is key oncogenic pathway in glioma." (PMID 28291820, 2017). "Here, our preliminary results suggest that Gab3 overexpression in human glioma mediates Akt activation and cancer cell proliferation." (PMID 28291820, 2017). "Gab3 mRNA and protein expression was significantly elevated in human glioma tissues and glioma cells." (PMID 28291820, 2017). "In order to study the potential effect of Gab3 on human glioma cells in vitro, shRNA strategy was applied." (PMID 28291820, 2017). "Together, we conclude that Gab3 overexpression in human glioma mediates Akt activation and cancer cell proliferation." (PMID 28291820, 2017). "In both established (U251MG cell line) and primary human glioma cells (“Glioma cells”),Gab3 mRNA and protein expression level was significantly higher than that in the primary human astrocytes (“Astrocytes”)." (PMID 28291820, 2017). "The preclinical results of our study suggest that Gab3 should be a novel oncogenic protein for human glioma." (PMID 28291820, 2017). "It should be noted that exogenous Gab3 overexpression only increased glioma cell proliferation by 20–30%." (PMID 28291820, 2017). "In the primary human glioma cells, siRNA-mediated knockdown of Gab3 also inhibited Akt activation." (PMID 28291820, 2017). "There results suggest that Gab3 knockdown inhibits U251MG glioma cell proliferation." (PMID 28291820, 2017). "This current study tested expression and potential biological functions of Gab3 in human glioma." (PMID 28291820, 2017). "In order to test the potential effect of Gab3 on glioma cell proliferation in vivo." (PMID 28291820, 2017). "Our results showing that Gab3 overexpression in human glioma mediates Akt activation and cancer cell proliferation suggest that Gab3 could be a novel oncogenic protein for glioma." (PMID 28291820, 2017). "Thus, knockdown of Gab3 inhibits proliferation of the primary human glioma cells." (PMID 28291820, 2017). "Interestingly, Gab3 didn’t form a complex with SHP2 in above glioma cells." (PMID 28291820, 2017). "This could be due to the fact that basal Gab3 expression is already high in glioma cells." (PMID 28291820, 2017). "Therefore, Gab3 could be a novel oncotarget protein for glioma." (PMID 28291820, 2017). "As discussed, a set of three distinct Gab3 shRNAs (“shGab3-a/-b/-c”) with non-overlapping sequences were introduced to U251MG glioma cells." (PMID 28291820, 2017). "First, Gab3 mRNA and protein expression was significantly elevated in both human glioma tissues and glioma cells, yet its level was quite low in normal brain tissues and human astrocytes." (PMID 28291820, 2017). "Transfection of two applied Gab3 siRNAs (“siGab3-a/-b”) efficiently downregulated Gab3 mRNA (but not Gab1) in the primary glioma cells." (PMID 28291820, 2017). "One other reason could be that Gab3 appears not required for Erk activation in glioma cells." (PMID 28291820, 2017).
ovarian carcinoma (2 papers, 2021 to 2022). A malignant neoplasm originating from the surface ovarian epithelium. "Moreover, in the mechanical regulation of OSBPL members, a recent study showed that GAB2 and GAB3, co-expressed with the OSBPL gene family were interrelated with much-shorter progression-free survival in ovarian cancer." (PMID 34829830, 2021).
bladder cancer (1 paper, 2022). "Few studies had reported that the six genes (TBXAS1, GYPC, HPGDS, GAB3, ADORA3, and FOLR2) had strong correlation with bladder cancer." (PMID 36275756, 2022).
Rectal prolapse (1 paper, 2019). Protrusion of the rectal mucous membrane through the anus. "A comparison of WT, Gab2−/−, Gab3−/−, and Gab2/3−/− mice showed that maximal Lcn-2 increase was observed in double knockout mice (average of 26-fold), whereas mice with rectal prolapse had high Lcn-2 levels, but high Lcn-2 levels did not predict rectal prolapse." (PMID 30936879, 2019).
type 1 diabetes (1 paper, 2018). "Here we found that risk variants of two genes, SH2B3 and GAB3, were more predictive of type 1 diabetes in African American subjects." (PMID 29540798, 2018).
tumor (6 papers, 2017 to 2023). "The upregulated genes including GAB3, SLC8A1, KCNMA1, and ZNF471 following CFP1 knockdown, were expressed at low levels in tumor tissues and were associated with favorable prognosis of LUAD patients." (PMID 37735441, 2023). "qRT-PCR assay results demonstrated that Gab3 mRNA expression in the tumor tissues was significantly higher than that in the normal brain tissues." (PMID 28291820, 2017). "In our study, upregulation of LINC00324, GAB3 as well as IKZF1 in TAM low-risk group could predict a better prognosis, suggesting the potential anti-tumor immunology role in the TME." (PMID 33738286, 2021). "Gab3 mRNA level was about four times higher in tumor tissues." (PMID 28291820, 2017). "Importantly, growth of U251MG tumor in vivo was remarkably inhibited when expressing Gab3 shRNA." (PMID 28291820, 2017). "The positional candidate gene GAB3 is a member of the GRB2 binder family that includes scaffolding/docking proteins involved in signaling pathways mediated by growth factors, cytokines, and antigen receptors, and has roles in immune response and tumor cell proliferation." (PMID 31766405, 2019).
cancer (3 papers, 2017 to 2023). A tumor composed of atypical neoplastic, often pleomorphic cells that invade other tissues. "Akt activation in cancer tissues was also suppressed by Gab3 shRNA." (PMID 28291820, 2017). "Next, we tested the potential effect of Gab3 on primary cancer cells." (PMID 28291820, 2017). "The scramble control siRNA (“si-SCR”) didn’t affect Gab3 expression and cancer cell proliferation." (PMID 28291820, 2017). "Moreover, a number of target genes of miR-155 affect other cancer-related processes, such as cell growth and survival (CCND1 and GAB3), cell adhesion junction (ANKRD6 and SMAD2), proliferation (SOCS1 and STAT3), and apoptosis (TP53BP1)." (PMID 31744065, 2019).
GAB3 also shares sentences with these, for which no sentence is quoted: colorectal cancer (1 paper); infection (1); lung carcinoma (1).